DTX3L (deltex E3 ubiquitin ligase 3L)
Description:
E3 ubiquitin-protein ligase which, in association with ADP-ribosyltransferase PARP9, plays a role in DNA damage repair and in interferon-mediated antiviral responses. Monoubiquitinates several histones, including histone H2A, H2B, H3 and H4. In response to DNA damage, mediates monoubiquitination of 'Lys-91' of histone H4 (H4K91ub1). The exact role of H4K91ub1 in DNA damage response is still unclear but it may function as a licensing signal for additional histone H4 post-translational modifications such as H4 'Lys-20' methylation (H4K20me). PARP1-dependent PARP9-DTX3L-mediated ubiquitination promotes the rapid and specific recruitment of 53BP1/TP53BP1, UIMC1/RAP80, and BRCA1 to DNA damage sites. By monoubiquitinating histone H2B H2BC9/H2BJ and thereby promoting chromatin remodeling, positively regulates STAT1-dependent interferon-stimulated gene transcription and thus STAT1-mediated control of viral replication. Independently of its catalytic activity, promotes the sorting of chemokine receptor CXCR4 from early endosome to lysosome following CXCL12 stimulation by reducing E3 ligase ITCH activity and thus ITCH-mediated ubiquitination of endosomal sorting complex required for transport ESCRT-0 components HGS and STAM. In addition, required for the recruitment of HGS and STAM to early endosomes. In association with PARP9, plays a role in antiviral responses by mediating 'Lys-48'-linked ubiquitination of encephalomyocarditis virus (EMCV) and human rhinovirus (HRV) C3 proteases and thus promoting their proteasomal-mediated degradation.
Synonyms: BBAP; RNF143
Tractability: Small molecule: it has a high-quality binding pocket. Antibody: UniProt places it where antibodies can reach, with high confidence. PROTAC: UniProt records ubiquitination sites on it; ubiquitination databases record sites on it; its protein half-life has been measured.
Gene: Protein-coding gene on chromosome 3 (122,564,338 to 122,575,203, forward strand). Ensembl gene ENSG00000163840.
Subcellular location: Cytoplasm; Nucleus; Early endosome membrane; Lysosome membrane
Subcellular location (Human Protein Atlas): Cytosol; Nucleoplasm
Pathways (Reactome):
Immune System: Antigen processing: Ubiquitination & Proteasome degradation
Gene Ontology:
Molecular function: enzyme binding; enzyme inhibitor activity; histone binding; histone H4K91 ubiquitin ligase activity; histone ubiquitin ligase activity; protein ADP-ribosyltransferase-substrate adaptor activity; protein binding; STAT family protein binding; ubiquitin protein ligase activity; ubiquitin-like protein ligase binding; ubiquitin-protein transferase activity
Biological process: DNA damage checkpoint signaling; DNA repair-dependent chromatin remodeling; double-strand break repair; endosome to lysosome transport; negative regulation of ubiquitin-protein transferase activity; positive regulation of chromatin binding; positive regulation of defense response to virus by host; positive regulation of DNA-templated transcription; positive regulation of protein binding; positive regulation of protein localization to early endosome; positive regulation of protein localization to nucleus; positive regulation of receptor catabolic process; protein autoubiquitination; protein K48-linked ubiquitination; ubiquitin-dependent protein catabolic process; Notch signaling pathway; protein ubiquitination
Cellular component: cytoplasm; cytosol; early endosome; early endosome membrane; lysosomal membrane; lysosome; nucleoplasm; nucleus; protein-containing complex
Genetic constraint (gnomAD): Loss-of-function variants: 31 observed, 61.01 expected, observed/expected ratio (o/e) 0.51, 90% interval 0.38 to 0.69. The upper end of that interval is the gene's LOEUF score, 0.69, which puts it in group 2 of 6, group 1 being the genes least tolerant of losing a copy. Missense variants: 797 observed, 899.53 expected, observed/expected ratio (o/e) 0.89, 90% interval 0.83 to 0.94. Synonymous variants: 286 observed, 328 expected, observed/expected ratio (o/e) 0.87, 90% interval 0.79 to 0.96.
Homologues: Orthologues: chimpanzee DTX3L (99% identical), macaque DTX3L (91% identical), dog DTX3L (66% identical), rabbit DTX3L (66% identical), pig DTX3L (65% identical), rat Dtx3l (59% identical), guinea pig DTX3L (59% identical), mouse Dtx3l (58% identical), tropical clawed frog dtx3l (28% identical), zebrafish dtx3lb.2 (25% identical), zebrafish dtx3lb.3 (19% identical), zebrafish dtex3lb.1 (11% identical). Paralogues in human: DTX2 (17% identical), DTX4 (17% identical), DTX3 (16% identical), DTX1 (16% identical).
Diseases named in the same sentence as DTX3L in open-access papers:
DTX3L is named in the same sentence as 44 diseases in open-access papers, as found by Europe PMC text mining. Sharing a sentence is not in itself a finding about the gene and the disease. The quoted sentences say what the papers report.
viral infection (8 papers, 2019 to 2025). "Collectively, these data indicate that DTX3L selectively promotes the K48-linked polyubiquitination of FPN1 to induce FPN1 degradation during viral infection." (PMID 40595467, 2025). "Parp9 and Dtx3l have been recently implicated in enhancing interferon signaling and controlling viral infection." (PMID 31057555, 2019). "NF-κB inhibitors (JSH-23 and QNZ), JAK1 inhibitor itacitinib, and Ifnar1 deficiency blocked viral infection-induced DTX3L expression, suggesting that viruses activate NF-κB and IFNAR-JAK to upregulate DTX3L." (PMID 40595467, 2025). "In our study, DTX3L selectively facilitates the K48-linked ubiquitination and protein degradation of FPN1, thus disrupting host iron withholding during viral infection." (PMID 40595467, 2025). "Compared with the host systemic iron regulator hepcidin secreted by the liver, which degrades FPN1 within 4 h following infection, DTX3L is rapidly induced after viral infection, robustly promoting FPN1 degradation." (PMID 40595467, 2025). "Next, we confirmed that viral infection induced DTX3L expression at both the mRNA and protein levels in macrophages." (PMID 40595467, 2025). "PARP9 and DTX3L form a tight complex that has suggested roles in DNA repair, as well as in the response to bacterial or viral infection and carcinogenesis." (PMID 38834853, 2024). "This is of particular importance given that PARP14 has been reported to have a crucial role in responding to coronavirus infection and mediating inflammation, while PARP9/DTX3L has been indicated in controlling viral infection and protecting against Mycobacterium tuberculosis." (PMID 38834853, 2024). "Here we show that viral infections facilitate the polyubiquitination and degradation of ferroportin (FPN1, the only cellular iron exporter) by upregulating the host E3 ubiquitin ligase DTX3L, leading to an elevation in cellular iron levels." (PMID 40595467, 2025). "Interestingly, proteomics directly revealed details on the immune defense against viral infections, including drastic increase in antigen CD177, Integrin alpha‐M (ITGAM) as well as the complex‐forming E3 ubiquitin‐protein ligase DTX3L and PARP9." (PMID 37519267, 2023). "Next, given that DTX3L is an active E3 ubiquitin ligase and that PARP9 and DTX3L have been reported to regulate ubiquitination in response to viral infection, we also investigated if we could observe any changes to ubiquitination after IFN treatment." (PMID 38834853, 2024).
prostate carcinoma (7 papers, 2015 to 2025). A carcinoma that arises from epithelial cells of the prostate gland. "We further show that DTX3L overexpression contributes to HR deficiency and sensitizes prostate cancer cells to synthetic lethality by PARP inhibitors." (PMID 39632881, 2024). "Accordingly, we demonstrate that DTX3L overexpression sensitizes prostate cancer cells to synthetic lethality by PARP inhibitors, highlighting that DTX3L overexpression indicates sensitivity to PARP inhibitors in cancers such as prostate cancer." (PMID 39632881, 2024). "In prostate cancer cells with DTX3L overexpression, the negative regulatory effect of TIRR on 53BP1 is impaired, which induces HR deficiency and chromosomal instability and results in high sensitivity to poly (ADP-ribose) polymerase (PARP) inhibitors." (PMID 39632881, 2024). "We further show that TIRR expression is decreased by DTX3L overexpression in prostate cancer, which inhibits HR and promotes chromosomal instability." (PMID 39632881, 2024). "We further examined TIRR and DTX3L protein expression in specimens from a cohort of prostate cancer patient (n = 44) using immunohistochemistry (IHC)." (PMID 39632881, 2024). "We noticed that both DTX3L and TIRR mRNA expression levels were increased in tumor tissues compared to normal tissues from The Cancer Genome Atlas (TCGA) prostate cancer datasets, and this increase was associated with the progression of prostate cancer." (PMID 39632881, 2024). "Although a recent in vitro study showed the effect of DTX3L via STAT1 and IRF-1 in prostate cancer cells, in vitro studies on Dtx3l/DTX3L functions are limited to solid tumors, and in vivo studies are further limited." (PMID 26033450, 2015). "To test whether Dtx3L/Parp9 contributes to AR-regulated gene expression in prostate cancer cells, we engineered VCaP cells with a Dox-inducible shRNA to Dtx3L and used the lines for transcriptomic analysis." (PMID 33976187, 2021). "The fact that DTX3L was overexpressed in prostate cancer patient samples and that DTX3L overexpression inhibited HR and caused chromosomal instability prompted us to explore whether DTX3L overexpression sensitizes prostate cancer cells to synthetic lethality by PARP inhibitors." (PMID 39632881, 2024). "The crosstalk between IFN and androgen signaling appears to be bidirectional given that IFN can induce Dtx3L/Parp9, and AR can repress IFN signaling through induction of genes such as SOCS3 in prostate cancer cells." (PMID 33976187, 2021). "It is interesting to note that although DTX3L contains a DTC domain, prostate cancer cells lacking DTX3L still undergo androgen-induced AR degradation." (PMID 40681873, 2025). "Although the TIRR mRNA expression level was increased in prostate cancer, the protein was almost absent due to high expression of DTX3L." (PMID 39632881, 2024). "The overexpression of DTX3L promotes the phosphorylation of STAT1 and represses the transcription of IFN regulatory factor-1 (IRF-1), thus enhancing the proliferation, metastasis and chemoresistance of prostate cancer cells." (PMID 36614304, 2023). "The overexpression of DTX3L and BAL1 promotes the phosphorylation of STAT1 and represses the transcription of IFN regulatory factor-1 (IRF-1), thus enhancing the proliferation, metastasis, and chemoresistance of prostate cancer cells." (PMID 34513839, 2021).
melanoma (6 papers, 2015 to 2023). A malignant, usually aggressive tumor composed of atypical, neoplastic melanocytes. "The regulatory mechanism underlying the invasion and metastasis of melanoma by DTX3L involves the focal adhesion kinase (FAK)/PI3K/AKT signal transduction, but not the MEK/ERK pathway." (PMID 34513839, 2021). "DTX3L has been recently linked to cancer due to its role in promoting metastasis of melanoma via activation of the FAK/PI3K/AKT signaling pathway." (PMID 29350614, 2018). "Both increased DTX3L (Deltex-3-like) level in melanoma cells and DTX3L-mediated regulation of invasion and metastasis in melanoma through FAK/PI3K/AKT but not MEK/ERK signaling was demonstrated." (PMID 27533251, 2016). "DTX3L protein expression levels were immunohistochemically analyzed in vivo in human nevi (n = 22), primary melanomas (n = 54) and metastatic melanomas (n = 20)." (PMID 26033450, 2015). "Our previous DNA microarray analysis in a benign melanocytic tumor and a melanoma from a RET-mouse showed increased levels of Dtx3l transcript in melanoma." (PMID 26033450, 2015). "The present in vitro and in vivo study newly clarified a function as well as expression level of DTX3L in murine and human melanomas." (PMID 26033450, 2015). "In contrast, nevi classified as high or moderate expression of DTX3L were obtained in 98% of the primary melanomas and 90% of the metastatic melanomas." (PMID 26033450, 2015). "Our in vivo study showed increased expression levels of Dtx3l in melanomas compared to the levels in murine benign melanocytic tumors in RET-mice." (PMID 26033450, 2015). "Our results obtained for murine and human melanoma cells showed that depletion of Dtx3l/DTX3L decreased the activity of Fak/FAK, Pi3k/PI3K and Akt/AKT." (PMID 26033450, 2015). "Our results suggest that the expression level of DTX3L protein, which is expressed in cytoplasmic areas of human melanoma cells, is a potential biomarker for melanoma in humans." (PMID 26033450, 2015). "DTX3L transcript expression levels in all of the melanoma cell lines (MNT-1, G361, A375P, A375M and SK-Mel28) were significantly higher than the level in NHEM cells." (PMID 26033450, 2015). "We next examined DTX3L transcript and protein expression levels in 6 human melanoma cell lines and NHEM cells." (PMID 26033450, 2015). "Real-time PCR analysis of tumors in RET-mice showed that Dtx3l transcript levels in melanomas were about 4-fold higher than those in benign tumors." (PMID 26033450, 2015). "In summary, our study suggested for the first time that Dtx3l/DTX3L is a potential therapeutic target as well as a potential biomarker for melanoma." (PMID 26033450, 2015). "Immunoblot and immunohistochemical analyses also showed that Dtx3l protein expression levels in melanomas were increased compared with those in benign melanocytic tumors from RET-mice." (PMID 26033450, 2015). "Depletion of DTX3L in murine and human melanoma cells resulted in decreased activity of FAK/PI3K/AKT signaling and reduced invasion and metastasis of murine and human melanoma cells." (PMID 26654227, 2015). "Our in vitro study showed demonstrated increased expression levels of DTX3L in melanoma cell lines compared to the level in NHEM cells in humans." (PMID 26033450, 2015). "Immunohistochemical analysis of human tissues showed that more than 80% of the melanomas highly expressed DTX3L." (PMID 26033450, 2015). "More importantly, there was no nevus classified as high expression of DTX3L, while more than 80% of the melanomas were classified as high expression of DTX3L in our immunohistochemical analysis of human tissues." (PMID 26033450, 2015). "Our results showed higher expression levels of DTX3L in melanomas than in nevi in humans." (PMID 26033450, 2015). "Moreover, our in vivo study showed more than 80% suppression of lung metastasis in Dtx3l-depleted melanoma cells." (PMID 26033450, 2015). "Thus, DTX3L is clinically a potential therapeutic target as well as a potential biomarker for melanoma." (PMID 26033450, 2015).
melanoma (continued). "We next examined the function of DTX3L in human G361 melanoma cells." (PMID 26033450, 2015). "We next tried to clarify the function of Dtx3l in murine B16F10 melanoma cells." (PMID 26033450, 2015). "Thus, DTX3L regulating the FAK/PI3K/AKT pathway is a potential target for melanoma patients who have relapsed after BRAF-targeted therapy." (PMID 26033450, 2015). "We then tried to clarify the function of Dtx3l/DTX3L in melanoma." (PMID 26033450, 2015). "We finally tried to clarify the molecular mechanism of Dtx3l/DTX3L in melanoma." (PMID 26033450, 2015). "DTX3L is reported to regulate the ubiquitin modification of PARP family proteins (PARP1, PARP2, PARP9, PARP14), promoting proliferation, migration and chemotherapy resistance of lymphoma, glioma, and melanoma." (PMID 38304253, 2023). "Among these known regulators, DTX3L drew our interest as it activates expression of ISG15 and other IFN-responsive genes by regulating the mono-ubiquitination of histones and has been found to function as an oncogenic factor in metastasis of melanoma." (PMID 29350614, 2018). "Here we showed that levels of Dtx3l/DTX3L in spontaneous melanoma in RFP/RET-transgenic mice and human melanoma cell lines were significantly higher than those in benign melanocytic cells and primarily cultured normal human epithelial melanocytes, respectively." (PMID 26033450, 2015). "However, depletion of Dtx3l/DTX3L has a very limited effect on the activity of Mek/MEK and Erk/ERK in both murine and human melanoma cells." (PMID 26033450, 2015). "In summary, we demonstrated not only increased DTX3L level in melanoma cells but also DTX3L-mediated regulation of invasion and metastasis in melanoma through FAK/PI3K/AKT but not MEK/ERK signaling." (PMID 26033450, 2015). "Our results showed that Dtx3l/DTX3L-mediated regulation of melanoma metastasis is dependent on the FAK/PI3K/AKT pathway but not the MEK/ERK pathway." (PMID 26033450, 2015).
breast carcinoma (5 papers, 2018 to 2023). "(H) DTX3L mRNA expression is positively associated with ISG15 expression in human basal-like breast cancers." (PMID 29350614, 2018). "It was found that DTX3L is overexpressed in breast cancer, especially in triple-negative breast cancer, where it functions as a negative regulator of ATRA-induced growth inhibition of breast cancer cells." (PMID 36614304, 2023). "We evaluated the constitutive expression of IRF1/DTX3L mRNAs and proteins in 41 of our breast cancer cell-lines." (PMID 32384653, 2020). "Similar types of constitutive expression profiles of IRF1 and DTX3L mRNAs can be deduced from the RNA-seq results available for breast cancer tissues in the TCGA dataset." (PMID 32384653, 2020). "The analyses of two breast cancer datasets, TCGA and Curtis, indicated that DTX3L was overexpressed in IDC compared to normal breast." (PMID 29350614, 2018). "To reveal the expression of DTX3L in breast cancer tissues, we conducted in silico analysis of DTX3L mRNA expression in breast cancer using the Oncomine database." (PMID 29350614, 2018). "Due to these potential facts and the unknown function of DTX3L in breast cancer, we performed DTX3L knockdown studies to reveal its role in LIPG signaling in basal-like TNBC cells." (PMID 29350614, 2018). "DTX3L is found to be overexpressed in breast cancer, which functions as a negative regulator of ATRA-induced growth inhibition in breast cancer cells." (PMID 36980857, 2023). "Our functional data indicated that IRF1 and DTX3L exert opposite effects on ATRA-dependent growth inhibition of breast cancer cells, suggesting that they are part of a negative feedback loop." (PMID 32384653, 2020). "Functional knockdown studies indicate that IRF1 and DTX3L are part of a negative feedback loop controlling ATRA-dependent growth inhibition of breast cancer cells." (PMID 32384653, 2020). "Our studies have shown that DTX3L, a ubiquitin E3 ligase essential for IFN-stimulated expression of ISGs, is required for protecting LIPG protein from proteasome-mediated degradation in breast cancer cells." (PMID 29350614, 2018). "The expression and functional role of DTX3L in breast cancer have not yet been explored." (PMID 29350614, 2018). "Differential expression of DTX3L was not significant among different molecular subtypes of breast cancer, suggesting that DTX3L may play a role in other breast cancer subtypes in addition to its role in basal-like TNBC." (PMID 29350614, 2018).
diffuse large B-cell lymphoma (4 papers, 2015 to 2023). "DTX3L was originally identified as a binding partner of B aggressive lymphoma 1 (BAL1), a risk-related gene and protein in diffuse large B cell lymphoma (DLBCL)." (PMID 26033450, 2015). "DTX3L was originally identified as a binding partner of BAL1 (PARP9/ARTD9), which is an oncogenic factor in diffuse large B-cell lymphoma (DLBCL) with a prominent immune/inflammatory infiltrate." (PMID 36614304, 2023).